LY75 (lymphocyte antigen 75)
Description:
Acts as an endocytic receptor to direct captured antigens from the extracellular space to a specialized antigen-processing compartment (By similarity). Causes reduced proliferation of B-lymphocytes.
Synonyms: Ly-75; CD205; CLEC13B; DEC-205; GP200-MR6
Tractability: Antibody: its Gene Ontology location is reachable by antibodies, with high confidence; UniProt predicts a signal peptide or a membrane-spanning region. PROTAC: its protein half-life has been measured. Other modalities: a drug acting on it is in phase 2 or 3 trials.
Gene: Protein-coding gene on chromosome 2 (159,803,355 to 159,904,756, reverse strand). Ensembl gene ENSG00000054219.
Subcellular location: Membrane
Subcellular location (Human Protein Atlas): Golgi apparatus
Gene Ontology:
Molecular function: signaling receptor activity; transmembrane signaling receptor activity
Biological process: immune response; inflammatory response; receptor-mediated endocytosis
Cellular component: extracellular exosome; plasma membrane; membrane
Genetic constraint (gnomAD): Loss-of-function variants: 182 observed, 230.71 expected, observed/expected ratio (o/e) 0.79, 90% interval 0.7 to 0.89. The upper end of that interval is the gene's LOEUF score, 0.89, which puts it in group 3 of 6, group 1 being the genes least tolerant of losing a copy. Missense variants: 1,882 observed, 2,051 expected, observed/expected ratio (o/e) 0.92, 90% interval 0.88 to 0.95. Synonymous variants: 648 observed, 698.05 expected, observed/expected ratio (o/e) 0.93, 90% interval 0.87 to 0.99.
Homologues: Orthologues: chimpanzee LY75 (99% identical), guinea pig LY75 (82% identical), dog LY75 (81% identical), pig LY75 (79% identical), mouse Ly75 (77% identical), rat Ly75 (76% identical), rabbit LY75 (76% identical), tropical clawed frog ly75 (44% identical), zebrafish ly75 (36% identical). Paralogues in human: PLA2R1 (28% identical), MRC2 (26% identical), MRC1 (23% identical), CD302 (3% identical).
Diseases named in the same sentence as LY75 in open-access papers:
LY75 is named in the same sentence as 65 diseases in open-access papers, as found by Europe PMC text mining. Sharing a sentence is not in itself a finding about the gene and the disease. The quoted sentences say what the papers report.
breast carcinoma (6 papers, 2013 to 2025). "In other studies, LY75 was found to participate in controlling cellular phenotypes in breast cancer and thus their metastatic potential." (PMID 37468969, 2023). "Few reports suggest for possible role of LY75 in malignant diseases; thus, LY75 has been reported as suppressed in colorectal and breast cancer, but universally expressed in both bladder carcinomas and normal urothelium and induced in thymoma." (PMID 26871602, 2016). "The genes sharing these GO terms have been previously shown to be involved in breast cancer prognostic process (e.g., CXCR6, KIT, RUNX3) and also immune cell regulation (e.g., CD8B, DAPP1, LY75)." (PMID 33919884, 2021).
melanoma (6 papers, 2019 to 2024). A malignant, usually aggressive tumor composed of atypical, neoplastic melanocytes. "Moreover, a DC signature (CD14+CD2+LY75+) associated with stromal macrophages linked with antigen capture and presentation was found associated with long-term survival of melanoma patients." (PMID 37190135, 2023). "Overall, our study provides the first clinical evidence that Ly75 expression is significantly associated with melanoma patient survival and NK cell infiltration, suggesting that Ly75 could be a useful prognostic factor." (PMID 32397120, 2020). "Next, we investigated genes that exhibit correlated expression with Ly75 in melanoma using the SKCM-TCGA dataset and cBioportal." (PMID 32397120, 2020). "Promoter methylation was markedly increased in primary and metastasis melanoma compared to in normal tissues, suggesting the presence of a significantly negative correlation between mRNA expression and DNA methylation of Ly75." (PMID 32397120, 2020). "Overall, our findings are the first to suggest the clinical relevance of Ly75 expression in melanoma, as well as the potential of Ly75 as a therapeutic target for melanoma." (PMID 32397120, 2020). "In conclusion, this study provides evidence for the potential of using Ly75 expression as a prognostic marker for melanoma and its correlation with the infiltration and activation of NK cells." (PMID 32397120, 2020). "We identified 24 genes that are the most positively co-expressed with Ly75 in melanoma." (PMID 32397120, 2020). "Therefore, this study systematically investigated Ly75 mRNA expression and its correlation with cancer prognosis in melanoma patients." (PMID 32397120, 2020). "Ly75 expression was significantly downregulated in skin cutaneous melanoma (SKCM), and its expression was positively correlated with the survival rates of patients with SKCM in multiple datasets, implicating that the downregulated expression of Ly75 affects melanoma malignancy." (PMID 32397120, 2020). "This study demonstrated a significant negative association between lower mRNA expression and higher DNA methylation of the Ly75 gene, suggesting that Ly75 may be involved in melanoma progression." (PMID 32397120, 2020). "Therefore, this study investigated the clinical relevance of Ly75 expression on the survival rates of patients with melanoma by analyzing data in an integrated and systematic manner using various databases." (PMID 32397120, 2020). "Interestingly, by performing spatially resolved transcriptomic analysis of CD14+ cells from different localization in melanoma tumor sections, the group of K. Palucka identified a DC signature (CD14+CD2+LY75+) in the stroma linked with antigen capture and presentation." (PMID 37190135, 2023). "Hence, LY75 could be a candidate prognostic biomarker in melanoma patients." (PMID 36533709, 2023). "As such, although the effects of Ly75 on anti-tumor responses and its role as a cancer immunotherapy have been investigated, the roles and clinical relevance of Ly75 expression in melanoma have not yet been studied." (PMID 32397120, 2020). "Although Ly75 expression also regulates tumor metastasis in various types of cancer, including ovarian cancer, the roles and clinical significance of Ly75 in melanoma have not yet been studied." (PMID 32397120, 2020). "Moreover, Ly75 expression in melanoma and normal skins, including sun-exposed and non-sun-exposed skin, was analyzed using datasets from TCGA TARGET GTEx in the UCSC Xena Browser." (PMID 32397120, 2020).
Obesity (6 papers, 2014 to 2025). Accumulation of substantial excess body fat. "The expression of the LY75 gene, responsible for the synthesis of lymphocyte antigen 75, is characterized by resistance to obesity in diabetes-prone mice." (PMID 41465472, 2025). "Endevour ranked Ly75 (lymphocyte antigen 75) and Itgb6 (integrin beta 6) as the top two candidate genes for Pbwg1.5 using training genes related to obesity." (PMID 25398139, 2014). "Until now, Ly75 has not been reported as a core gene underlying obesity." (PMID 30518881, 2018). "Therefore, the Ly75 and Itgb6 genes with immune function may be good candidate genes for our Pbwg1.5 that shows prevention of obesity when mice are fed both low-fat standard and high-fat diets." (PMID 25398139, 2014). "We previously revealed that the lymphocyte antigen 75 (Ly75) gene with an immune function is a putative QTG for Pbwg1.5, a quantitative trait locus (QTL) for resistance to obesity found from wild mice (Mus musculus castaneus)." (PMID 30518881, 2018). "On the other hand, the CIT provided statistical evidence that only the Ly75 gene in the liver mediates between genotype and white fat pad weight, suggesting that Ly75 is a putative QTG for Pbwg1.5 with a preventive effect on obesity." (PMID 29186889, 2017). "Thus, we conclude that Ly75 is surely a non-core gene involved in the omnigenic architecture of obesity." (PMID 30518881, 2018).
ovarian carcinoma (6 papers, 2016 to 2024). A malignant neoplasm originating from the surface ovarian epithelium. "In silico analysis of the TCGA data for ovarian cancer was also confirmative for the role of LY75 in modulating the Wnt/β-catenin pathway activity in EOC." (PMID 32156068, 2020). "In addition, an in vivo study shows that the depletion of Ly75-expressing DCs impairs tumor progression in ovarian cancer." (PMID 32397120, 2020). "Additionally, in ovarian cancer, in vivo depletion of Ly75-positive DCs impairs tumor progression." (PMID 32397120, 2020).
Autoimmunity (5 papers, 2012 to 2022). The occurrence of an immune reaction against the organism's own cells or tissues. "After preliminary studies, we selected three proteins essential for gonad development as potential targets for induced autoimmunity: gonadal soma-derived factor (Gsdf), growth differentiation factor 9 (Gdf9), and lymphocyte antigen 75 (Cd205/Ly75)." (PMID 25436775, 2014).
diabetes (4 papers, 2013 to 2025). "Interestingly, however, single nucleotide polymorphisms of the Ly75 antigen belong to the three single nucleotide polymorphisms most significantly associated with type 2 diabetes mellitus, leaving open a possible role of Ly75 in inflammatory disease." (PMID 24690414, 2014). "Using bioinformatics and machine learning techniques, we identified six key genes that are closely associated with vascular aging in diabetes: TFB1M, FOXRED2, LY75, DALRD3, PI4K2B, and NDOR1." (PMID 38809515, 2024). "The expression of TFB1M, FOXRED2, DALRD3, PI4K2B, and NDOR1 was negatively correlated with vascular aging in diabetes, while LY75 expression was positively correlated." (PMID 38809515, 2024). "We used machine learning to identify six key genes closely associated with vascular aging in diabetes: TFB1M, FOXRED2, LY75, DALRD3, PI4K2B, and NDOR1." (PMID 38809515, 2024).
Stroke (3 papers, 2018 to 2023). Sudden impairment of blood flow to a part of the brain due to occlusion or rupture of an artery to the brain. "Higher relative concentrations of plasma CLEC4G, CKAP4, and IL-6 were associated with higher stroke severity, whereas LY75 and ITGA11 showed an inverse association." (PMID 37468969, 2023). "The present study confirmed the positive associations between stroke severity and IL6 and CKAP4, but also elucidated novel associations, namely between CLEC4G, LY75 and ITGA11, which enrich the present knowledge of blood biomarkers associated with stroke." (PMID 37468969, 2023). "The biomarkers CLEC4G, CKAP4, IL6, LY75 and ITGA11 were found to be significantly associated with stroke severity as measured by mRS and in case of IL6 and ITGA11 also by NIHSS." (PMID 37468969, 2023). "LY75 and ITGA11 were associated with lower stroke severity and might serve as potential therapeutic targets for promoting tissue repair and recovery following stroke." (PMID 37468969, 2023).
bladder cancer (2 papers, 2016 to 2023). "In the in vitro activity study, nitidine chloride inhibited bladder cancer cells by downregulating the expression of Lymphocyte antigen 75 (LY75)." (PMID 37764364, 2023).
dilated cardiomyopathies (2 papers, 2020 to 2024). "Additionally, in patients with dilated cardiomyopathies, association of aberrant DNA methylation was observed with significant differences in expression of ADORA2A and LY75 mRNA." (PMID 38314203, 2024). "Additionally, epigenomic studies of dilated cardiomyopathy patients found that abnormal DNA methylation changed mRNA expression of LY75 and ADORA2A with later studies linking 517 loci with dilated cardiomyopathy." (PMID 33202590, 2020).
glioma (2 papers, 2019 to 2020). A benign or malignant brain and spinal cord tumor that arises from glial cells (astrocytes, oligodendrocytes, ependymal cells). "Three cancer types including SKCM, sarcoma (SARC), and low grade glioma (LGG) showed significant COX regressions for Ly75 mRNA expression (p < 0.01)." (PMID 32397120, 2020).
heart failure (2 papers, 2013). Inability of the heart to pump blood at an adequate rate to meet tissue metabolic requirements. "Our in vivo experiments clearly underline that reduced expression of LY75 and ADORA2A in cardiomyocytes leads to heart failure as observed in our patients." (PMID 23341106, 2013). "As a result, ly75-morphants developed late-onset heart failure with dilation of the atrium and reduced ventricular contractility beginning at the 96 h developmental stage (FS = 46 ± 5% at 48 hpf and 29 ± 4% at 96 hpf)." (PMID 23341106, 2013). "We detected methylation differences in pathways related to heart disease, but also in genes with yet unknown function in DCM or heart failure, namely Lymphocyte antigen 75 (LY75), Tyrosine kinase-type cell surface receptor HER3 (ERBB3), Homeobox B13 (HOXB13) and Adenosine receptor A2A (ADORA2A)." (PMID 23341106, 2013). "Since LY75 and ADORA2A were not previously known to be involved in DCM or heart failure pathogenesis and both showed significant downregulation in the myocardium of DCM patients, we investigated their functional roles by gene knockdown in zebrafish embryos." (PMID 23341106, 2013).
idiopathic dilated cardiomyopathy (2 papers, 2013 to 2019). Decreased function of the heart associated with cardiac enlargement and congestive heart failure, of unknown cause. "Genome-wide cardiac DNA methylation in idiopathic dilated cardiomyopathy patients revealed abnormal DNA methylation, which was related to important variations in the expression of lymphocyte antigen 75 (LY75) and adenosine receptor A2A (ADORA2A) mRNA." (PMID 31649728, 2019).
thymoma (2 papers, 2016 to 2026). A neoplasm arising from the epithelial cells of the thymus. "CD205 (DEC205/LY75) is a specific surface marker for thymoma that we have proposed, when combined with CD45, it is possible to strictly isolate a small number of tumour cells." (PMID 41344988, 2026).
colon cancer (1 paper, 2024). "Therefore, we speculate that AMACR and LY75 may inhibit tumor mutation burden in colon cancer and lead to decreased MSI levels, while the suppressed anti-tumor immune response will further reduce the risk of colon cancer recurrence and proliferation." (PMID 39726813, 2024).
Erythema nodosum (1 paper, 2016). An erythematous eruption commonly associated with drug reactions or infection and characterized by inflammatory nodules that are usually tender, multiple, and bilateral. "A LY75 locus variant has also been associated with erythema nodosum as an extra-intestinal manifestation of CD." (PMID 27965521, 2016).
leprosy (1 paper, 2017). Leprosy is a chronic infectious disease affecting primarily the skin and peripheral nervous system. "Similarly, 7 of the 9 SNPs significantly heterogeneous between T1R and leprosy were eQTLs in either whole blood, rs3774937 (NFKB1), rs10065637 (ANKRD55), rs11150589 (ITGAL) and rs2836878 (lncRNA ENSG00000235888) or multiple tissues, rs4664304 (LY75), rs113653754 (HLA-DQB1) and rs4768236 (LRRK2)." (PMID 28222097, 2017).
leukoplakia (1 paper, 2023). A white patch or plaque on a mucous membrane that cannot be characterized clinically or pathologically as any other disease. "We found 4 genes (LY75, ZNF83, ZNF160, ZNF331) common in leukoplakia and OSCC, while 9 genes appeared only in OSCC, suggesting their role in disease advancement." (PMID 37245006, 2023).
metastatic melanoma (1 paper, 2020). A melanoma that has spread from its primary site to another anatomic site. "Co-expression patterns of Ly75 and Ptprc in primary and metastatic melanoma were visualized using a heatmap." (PMID 32397120, 2020).
ovarian serous cystadenocarcinoma (1 paper, 2016). A malignant serous cystic epithelial neoplasm arising from the ovary. "Moreover, by using the cBioPortal online analytical tool which includes the TCGA ovarian serous cystadenocarcinoma database, we also found that LY75 displays the highest amplification rate in serous EOC, compared to all other cancer types." (PMID 26871602, 2016).
serous ovarian tumors (1 paper, 2016). "In the present study, we demonstrated that LY75 is overexpressed exclusively in HG serous ovarian tumors, as compared to LMP tumors and normal ovarian tissues." (PMID 26871602, 2016).
skin cutaneous melanoma (1 paper, 2020). "Although the roles of Ly75 in tumors have been reported both in vivo and in vitro, there has been no comprehensive analysis on the clinical relevance of Ly75 expression in skin cutaneous melanoma (SKCM)." (PMID 32397120, 2020). "However, clinical relevance of Ly75 expression in skin cutaneous melanoma (SKCM) have not been comprehensively studied." (PMID 32397120, 2020).
tumor (44 papers, 2006 to 2026). "Overexpression of EBV miR-BART1-5p in EBV-associated tumor cells can inhibit the expression of LY75, and promote tumor cells to get rid of the recognition and monitoring of CD4+ Th cells and CD80+ CTL cells." (PMID 32127936, 2020). "Interestingly, the acquisition of epithelial phenotype upon LY75 knockdown was associated with reducing the migration and invasion of EOC cells in vitro; however, the loss of LY75 expression significantly enhanced tumor cell colonization and expansion in vivo in IP xenograft mouse model." (PMID 26871602, 2016). "Here, we show that Ly75 gene ablation also directed the suppression of the Wnt/β-catenin pathway in tumor samples from mice IB-injected with SKOV3-E and SKOV3-E+M cells." (PMID 32679765, 2020). "Significant correlations were found between Ly75 expression and overall survival in most clinicopathological parameters, except for tumor stage 1." (PMID 32397120, 2020). "The proliferation marker Ki-67 was also induced in tumor tissues derived from mice injected with the LY75-knockdown cells, in agreement with our in vitro functional analyses." (PMID 26871602, 2016). "Moreover, to identify related factors that affect survival rates, we also investigated the correlation between Ly75 expression and tumor-infiltrating lymphocytes, especially NK cells, in the tumor microenvironment." (PMID 32397120, 2020). "Therefore, Ly75 is mainly expressed in infiltrating immune cells in the tumor environment of SKCM." (PMID 32397120, 2020). "Moreover, LY75 depletion in A2780s cells was associated with reduced capacity for in vivo EOC cell colonization, which also confirms the higher potential of epithelial cancer cells for distant colonization and metastatic tumor formation." (PMID 26871602, 2016). "The expression of TAPBPL, SERPINB9, RCAN1, TMBIM4, JUNB, IL4R, and LY75 is significantly up-regulated in tumor samples with their high expression associated with a poor outcome; the expression of MGST3 is down-regulated in tumor samples with its low expression associated with poor prognosis." (PMID 25133526, 2014). "Ly75 (also known as DEC-205 or CD205) is expressed in immune cells and cancers and involved in tumor immunity." (PMID 32397120, 2020). "Analysis of the data by TIMER shows that Ly75 expression had a significantly negative correlation with tumor purity in SKCM (cor." (PMID 32397120, 2020). "Although NK cells play important roles in anti-tumor responses, the role of Ly75 expression in NK cells has not yet been studied." (PMID 32397120, 2020). "In particular, Ly75 is predominantly expressed by dendritic cells (DCs), and plays a critical role in endocytosis and antigen presentation to T cells through major histocompatibility complex (MHC) molecules, thereby resulting in anti-tumor responses." (PMID 32397120, 2020). "A significant negative correlation was found between tumor purity and Ly75 expression, indicating that the Ly75 gene may be expressed by infiltrated immune cells in the tumor microenvironment (TME) of SKCM." (PMID 32397120, 2020). "Further studies are warranted to better understand the molecular mechanisms of LY75-mediated control on EOC cell morphology and metastatic potential, and possibly, its analogous functions in sustaining cellular phenotype and invasive capacities of tumor cells derived from other cancer types." (PMID 26871602, 2016).